FAP (fibroblast activation protein alpha)
Diseases named in the same sentence as FAP in open-access papers (continued):
Sharing a sentence is not in itself a finding about the gene and the disease.
tumor (continued). "Recent studies have explored radiolabelled FAP inhibitors or antibodies to FAP for tumour treatment." (PMID 41049848, 2025). "More recently, radiolabeled FAP inhibitors (FAPI) have demonstrated selective tumor targeting and encouraging early clinical outcomes." (PMID 40453074, 2025). "The included studies demonstrated that lutetium-177,yttrium-90 and actinium-225 (in combination therapy) labeled FAP inhibitors exhibit high tumor uptake, with varying but mostly sufficient retention and a favorable safety profile." (PMID 41463267, 2025). "The significant reduction in tumor uptake following the co-administration of unlabeled DOTA-FAPI-04 further confirms the specificity of [18F]AlF-H3RESCA-FAPI for FAP-expressing tumors." (PMID 40006089, 2025). "In a study on resistance to ICB immunotherapy (pembrolizumab) in metastatic GC, FAP+ CAFs were found to correlate positively with MDSCs in tumor tissues, mediating an immunosuppressive barrier through enhanced MDSC infiltration." (PMID 41164803, 2025). "While SSTR2a expression was more homogenous and mainly seen in regions with higher cellularity, FAP immunoreactivity was predominantly seen in tumour stroma and regions of lower cellularity." (PMID 39969538, 2025). "FAP is believed to contribute to tumor progression through its effects on extracellular matrix (ECM) remodeling, cell migration, invasion, and metastasis." (PMID 41373408, 2025). "Quantitative PCR showed the highest FAP transcript levels in bone, tumor, pancreas, salivary glands and bone marrow in both PC3 and healthy mice." (PMID 40000459, 2025). "FAP has been shown to play a pivotal role in drug resistance, immunosurveillance, and tumor invasion and growth by remodeling the tumor microenvironment." (PMID 40473461, 2025). "Antibody-drug conjugates (ADCs), such as OMTX705, can selectively deliver drugs to FAP+ CAFs, showing complete tumor growth inhibition when combined with chemotherapy." (PMID 40890855, 2025). "These were evaluated through 177Lu labeling, followed by biodistribution studies in SK-RC52.FAP tumor-bearing mice." (PMID 40438601, 2025). "Cytokine secretion: FAP + CAFs contribute to the creation of an immunosuppressive tumour microenvironment." (PMID 40741380, 2025). "More recently, 68Ga-FAPI PET/CT has been developed to target fibroblast activation protein (FAP), visualizing the tumor stroma with high sensitivity, often surpassing that of 18F-FDG for detecting primary and metastatic lesions." (PMID 41408360, 2025). "In conclusion, FAP expression in the mesenchyme reduces tumor killing by immune cells, and the depletion of FAP in combination with anti-tumor therapy will improve therapeutic efficacy." (PMID 40438601, 2025). "The high expression of FAP in the tumor mesenchyme influences the biological behavior of tumor cells and adjacent mesenchymal cells." (PMID 40438601, 2025). "Based on prior molecular docking data, this study identified FAP-2286, a compound targeting tumor fibroblast components, as the molecule of interest." (PMID 40430845, 2025). "Tumorigenesis and tumour growth were reduced in FAP knockout (Fap−/−) mice in both lung and colon cancer models." (PMID 39780187, 2025). "Treatment with Talabostat, an inhibitor of fibroblast activation protein (FAP) that reduces collagen production, resulted in significant inhibition of tumor growth." (PMID 39823457, 2025). "Next, we explore the pan-cancer differential expression of FAP comparing tumor tissues with normal prostate tissues using the online platform TIMER." (PMID 40438108, 2025). "Imaging FAP in the stroma represents a strategy to overcome tumor heterogeneity since CAFs are more genetically stable and often surround cancer cells that possess heterogeneous antigen expression." (PMID 39868181, 2025). "Some novel FAPI probes, such as FAPI‐46, have been designed to enhance FAP targeting by reducing molecular weight, which improves tumor penetration." (PMID 40656546, 2025).
tumor (continued). "FAP CAR-T cells have shown effective tumor suppression and resulted in decreased numbers of FAP-positive stromal cells in multiple tumor models." (PMID 40699667, 2025). "[89Zr]Zr-H15-Fc had the most rapid tumor localization, with uptake in FAP-expressing tumors being significantly greater than in negative tumors within 4 h." (PMID 40804296, 2025). "In contrast, 68Ga-FAPI-04 uptake showed significant inter-tumor heterogeneity, underscoring that stromal FAP expression is highly dependent on specific tumor types and their unique microenvironments, consistent with the known biological diversity of CAFs." (PMID 41408360, 2025). "This can be explained by the TGF-β-mediated upregulation of PD-L1 and downregulation of HLA-I in tumor models as shown by us and various reports suggesting the involvement of FAP in shaping the immune-suppressive TME landscape." (PMID 41233863, 2025). "Background/Objectives: Fibroblast activation protein (FAP) has gained tremendous traction as a target for tumor imaging and cancer treatment, while also playing a key role in fibrosis." (PMID 40430477, 2025). "In CAFs, different subpopulations can be divided according to the expression level of markers such as FAP, with high expression of FAP in CAFs inducing tumor cell proliferation, invasion and metastasis, and immune resistance." (PMID 40104498, 2025). "The result showed that LINC01711 is upregulated in tumor tissue and is specifically overexpressed in FAP+ CAFs." (PMID 40855046, 2025). "In breast cancer, FAP+ CAFs enhance invasiveness and diminish anti-tumor immune response, contributing to reduced patient survival." (PMID 38540204, 2024). "In the current investigation, using a sizeable clinical cohort of tumor samples, we have examined the intricate immunological signatures that accompany FAP expression within the TME." (PMID 39035007, 2024). "FAPI PET tracers bind specifically to the enzymatic domain of FAPα and can visualize tumor stroma formation." (PMID 39410013, 2024). "In spite of this wide range of more than 100-fold, we did not see a dramatic difference with respect to either the lysis of FAP+ tumor cells or release of cytokines." (PMID 39000348, 2024). "Utilizing IHC to determine FAP expression, we assessed nine distinct tumor types, linking FAP expression with progression-free survival (PFS)." (PMID 38558814, 2024). "In this respect, monomeric quinoline-based tracers that act as FAP inhibitors (FAPIs) demonstrated promising results in preclinical studies but also in clinical PET imaging in 15 different tumor entities." (PMID 39661209, 2024). "Our study reveals a role of the circRNA-induced fibroblast niche in tumor metastasis and highlights that targeting the circNOX4/FAP/IL-6 axis is a promising strategy for the intervention of NSCLC metastasis." (PMID 38459511, 2024). "Anti-FAP NIR-PIT significantly suppressed LL/2 tumor growth compared with anti-FAP Ab alone, rat IgG1 isotype control plus NIR-PIT light exposure, or an untreated control group." (PMID 38275890, 2024). "Here, we aimed to explore the effect of IL-17a on HSCs and the expression of their functional gene FAP in the tumor microenvironment and to show the cancer-promoting and pro-metastatic mechanism of IL-17a mediated through mesenchymal cells." (PMID 38740736, 2024). "A hallmark of CAFs is FAP, a cell surface serine protease essential for remodeling the ECM, which in turn promotes tumor cell invasion and migration." (PMID 38826849, 2024). "Our study provides novel mechanisms by which circNOX4 increases the expression of FAP, the key marker of fibroblast activation, thereby contributing to the tumor-promoting phenotypes of CAFs." (PMID 38459511, 2024). "Within its scope, this review summarizes the recent research progress of the FAP radiopharmaceuticals based on antibodies and peptides in tumor imaging and therapy." (PMID 38543239, 2024).
tumor (continued). "Among them, FAP is highly specific for expression on 90% tumor stroma (e.g, primary and metastatic cancers of the breast, lung, and colorectal cancer), and almost not expressed in benign tumors and normal tissues." (PMID 39281380, 2024). "With the increase of CDI, there were upward trends among TIDE, FAP, tumor immune exclusion and TMB, while a downward in T cell dysfunction." (PMID 38977778, 2024). "This study found that FAP expression is more PDAC-specific than glucose metabolism by comparing the tumor-to-background ratio in [18F]FDG and [18F]AIF-FAPI-74 PET/CT." (PMID 39365411, 2024). "The interaction between FBiTE and CD3+ effector T cells, as well as FAP+ targeted cells, resulted in the activation of T cells, their subsequent proliferation, and the induction of cytotoxicity leading to the death of FAP-positive A549 tumor cell lines." (PMID 38464532, 2024). "Fibroblast activation protein (FAP) is predominantly upregulated in various tumor microenvironments and scarcely expressed in normal tissues." (PMID 38558814, 2024). "FAP-based DNA vaccines can induce FAP-specific tumor-infiltrating lymphocytes to specifically clear CAFs and disrupt tumor tolerance." (PMID 38167055, 2024). "Radiolabeled FAPi tracers bind to FAP+ cells abundant in cancers and distinguish the tumor from surrounding normal structures in imaging." (PMID 38275890, 2024). "Tumor sections from all the mice were subjected to staining with hematoxylin and eosin (H&E) and anti-FAP alpha antibody." (PMID 39519118, 2024). "IHC established tumor (PanCK) and stromal regions (fibroblast activation protein, FAP) of the tumor, as well as cytotoxic T cell (CD8) and macrophage (CD68) infiltration." (PMID 38517140, 2024). "Fibroblast activation protein (FAP), a transmembrane glycoprotein expressed by CAFs, has been suggested as a target for tumor diagnosis and therapy." (PMID 39595051, 2024). "In this study, we established a murine tumor model that includes CAFs and treated it with FAP-targeted NIR-PIT." (PMID 38555315, 2024). "Crucially, the inhibition of CCN2 was observed to significantly disrupt the feedback loop between tumor cells and the FAP+ fibroblasts, consequently mitigating its potential for tumor metastasis." (PMID 39095854, 2024). "Aside from tumour stroma and tumour cells, fibroblasts in actively remodelling tissues, such as chronic inflammation and fibrotic tissue, also exhibit upregulated FAP expression." (PMID 39629119, 2024). "Preclinical studies involving 68Ga- or 177Lu-labeled FAP-RGD, synthesized from FAP-2286 and c(RGDfK), demonstrated strong binding affinity, increased tumor uptake, and prolonged retention compared to their monomeric counterparts." (PMID 39598465, 2024). "FAP-2286 is a FAP-binding cyclic peptide, and exhibits prolonged tumor retention, which is an important prerequisite for TRT." (PMID 38360704, 2024). "FAP itself also directly supports tumor growth, invasion, and metastasis through extracellular matrix remodeling." (PMID 38275890, 2024). "FAP inhibitors (FAPIs) bind specifically to FAP and are used for tumor-targeted diagnosis and therapy." (PMID 39281380, 2024). "FAP has been shown to promote tumor progression and to be a predictor of poor overall survival for multiple cancer types, including colon cancer, prostate cancer, pancreatic ductal adenocarcinoma, ovarian cancer, and NSCLC." (PMID 38540158, 2024). "Fibroblast activation protein-α (FAP) demonstrate an elevated expression level in CAFs, which serve as the predominant component of the tumor stroma." (PMID 38464532, 2024). "It has also been shown that targeting FAP using CAR-T cells can effectively increase the killing of tumor cells in vitro." (PMID 39030445, 2024). "In contrast, the 10-week-old Panc-1-fl model revealed FAP stain of the tumor cells and also the elongated stromal cells (blue arrows)." (PMID 38891809, 2024).
tumor (continued). "Based on published research and our own observations, FAP is commonly found in CAFs, a prevalent cell population in the tumor microenvironment (TME)." (PMID 39035007, 2024). "LNC1004 is a fibroblast activation protein (FAP)-targeting radiopharmaceutical, conjugated with the albumin binder Evans Blue, which has demonstrated enhanced tumor uptake and retention in previous preclinical and clinical studies." (PMID 38825657, 2024). "One of these antibodies is engineered to target FAP for precise localization, while the other is designed to interact with molecules influencing tumor apoptosis or necrosis." (PMID 38543239, 2024). "To determine the relationship between CAFs and CD4+ TILs, we fluorescently stained CD4 and fibroblast-activation protein (FAP), a marker for CAFs in tumor tissue from 4T1 mouse model." (PMID 39543650, 2024). "When EC patients were classified based on tumor grade, significant elevation in the levels of angiopoietin-2 (p = 0.015), FAP (p = 0.033), FGF-1 (p = 0.0004), and VEGF-A (p = 0.018) were observed in the more advanced grade 3 tumors compared to grade 1 tumors." (PMID 39511039, 2024). "Intriguingly, we observed that EMT-subtype tumor cells showed the most active interactions with FAP+ fibroblasts (203 receptor-ligand pairs), while Metab-subtype cells only had half the number of interaction pairs." (PMID 39095854, 2024). "This demonstrates the potential of utilizing bispecific PSMA/FAP tracers to improve the tumor uptake." (PMID 38398552, 2024). "The FAP+PDPN+ population of CAFs is enriched at the outer edge of the tumor, in close contact with T cells, whereas the FAP+PDPN− population of cancer-associated pericytes (CAPs) is located around the vessels." (PMID 38715072, 2024). "In summary, after more than 30 years of continuous research and development, FAP has not only been characterized as an effective biomarker in disease diagnosis and prognosis but also as a promising target for tumor therapy." (PMID 39758423, 2024). "The ex vivo analysis of the FAP expression in the tumors corroborates the in vivo findings, confirming the expected endogenous expression of FAP within these tumor cells." (PMID 39335703, 2024). "Some pilot studies on radiolabelled FAP diagnostic and therapy agents have been performed in RAI-refractory patients, with good tumour uptake and promising results, paving the way for further investigations." (PMID 39336848, 2024). "We analyzed the efficacy of this therapy and describe changes in tumor immunity after FAP-targeted NIR-PIT in a syngeneic mouse tumor model." (PMID 38555315, 2024). "[99mTc]Tc-L1 and [99mTc]Tc-L2 were then assessed through in vitro and in vivo studies to refine potential tumor imaging agents targeting FAP." (PMID 38695960, 2024). "Heterogeneity in FAP distribution was evident, presenting as thick, moderate, or thin strands, even within the same tumor subtypes." (PMID 38558814, 2024). "Vaccination with eNVs-FAP targeting FAP + CAFs significantly reduces CAFs in tumor-bearing mice and reprograms the immune-suppressive TME, thereby inhibiting tumor growth(P = 0.0086)." (PMID 39262952, 2024). "While some cases had equivalent FAP area coverage, the distribution variations highlighted the complex relationship between heterogeneity and tumor morphology." (PMID 38558814, 2024). "Consistent with the imaging results, tumor growth was inhibited in mice treated with FAP-CAR T cells." (PMID 39086477, 2024). "In conclusion, FAP has emerged as a prominent target in the pursuit of tumor-specific interventions, demonstrating promising outcomes in tumor imaging and therapy research." (PMID 38543239, 2024). "Most importantly, molecular probes targeting FAP can be specifically located in tumors to achieve tumor imaging and treatment." (PMID 39281380, 2024).
tumor (continued). "This vaccine inhibited tumor growth by eliciting a potent, specific cytotoxic T lymphocyte immune response against tumor cells and FAP-expressing CAFs, reshaping the immunosuppressive TME in a breast cancer model." (PMID 38835784, 2024). "CAFs therefore, are a reasonable target for NIR-PIT, and we previously established CAF-targeted NIR-PIT using FAP as a target which successfully and selectively depleted CAFs, resulting in tumor regression." (PMID 38555315, 2024). "Depletion of FAP+ stromal as well as FAP+ myeloid cells effectively suppressed tumor growth in bone marrow chimeras, suggesting that the depletion of both cell types in one treatment is an effective therapeutic approach." (PMID 38275890, 2024). "IL-2v was fused to several kinds of mAbs targeting PD-1, carcinoembryonic antigen (CEA), and fibroblast activation protein alpha (FAP) to target PD-1+ T cells, tumor cells, and cancer-associated fibroblasts, respectively." (PMID 39218982, 2024). "In recent years, radionuclide labelled probes targeting FAP were widely used in tumor diagnosis and treatment." (PMID 39281380, 2024). "[177Lu]Lu-FAP-2286 demonstrated prolonged tumor retention, with an effective half-life of approximately 44 h in bone metastases." (PMID 39765634, 2024). "In murine models, the pivotal role of FAP-positive CAFs in promoting tumor growth by suppressing antitumor immunity has been established." (PMID 38558814, 2024). "Moderate-strong FAP expression in tumor stroma was significantly more prevalent in CCA than HCC (p < 0.001), metastatic HCC (p = 0.005), HCA (p < 0.001) and FNH (p < 0.001)." (PMID 39664608, 2024). "The expression of FAP in a wide variety of tumor types has made it a potential target for cancer imaging and radionuclide therapy in recent years." (PMID 39770488, 2024). "We discovered that although [68Ga]Ga-FAPI-04 has a higher binding affinity toward FAP and higher tumor uptake, both of our pyridine-based tracers have lower uptake in blood, muscle, and bone, leading to much higher tumor-to-background contrast ratios." (PMID 38398552, 2024). "With its introduction into clinical practice, Clovis Oncology embarked on the radiolabeling of FAP-2286 with gallium-68 for clinical tumor imaging." (PMID 38543239, 2024). "We accessed as many specimens as possible for secondary IHC (FAP staining) of the primary tumor tissue." (PMID 38575990, 2024). "FAP plays a vital role in tissue remodeling and has demonstrated an ability to support tumor cell development." (PMID 39511039, 2024). "Further optimization on the selection of linkers should be explored to improve the binding affinity, pharmacokinetics, and tumor uptake of the bispecific PSMA/FAP tracers." (PMID 38398552, 2024). "Cancer cells were coated with CXCL12, while FAP-positive CAFs were the principal source of CXCL12 in the tumor." (PMID 38892190, 2024). "The observed immunopositivity in the tumor cells was consistent with the expected endogenous expression of FAP." (PMID 39335703, 2024). "Since this treatment targets FAP expressed in CAFs, it would be ideal to use a tumor-bearing model where these are consistently present." (PMID 39519118, 2024). "We validated our immunohistochemistry (IHC) results by establishing the correlation between protein levels and FAP mRNA expression, as determined by RNAseq in fresh and archived tumor samples." (PMID 38558814, 2024). "In summary, VEGF-A aligned with all the tumor characteristics we evaluated, FAP was associated with tumor grade, size, and MMR status, and angiopoietin-2 was associated with tumor grade and MMR status." (PMID 39511039, 2024). "In patient samples, FAP is expressed on CAFs, a heterogeneous cell population of the tumor microenvironment with a characteristic radiobiologic behavior." (PMID 39266288, 2024). "Yet, PSCs influence tumor formation and promote the invasion of mouse fibroblasts, as observed by a higher percentage of mouse Collagen I and FAPα and lower NuMA staining." (PMID 39410013, 2024).